CEACAM16 (CEA cell adhesion molecule 16, tectorial membrane component)
Description:
Required for proper hearing, plays a role in maintaining the integrity of the tectorial membrane.
Synonyms: CEAL2; DFNA4B; DFNB113
Tractability: Antibody: UniProt places it where antibodies can reach, with high confidence; UniProt predicts a signal peptide or a membrane-spanning region; its Gene Ontology location is reachable by antibodies, with medium confidence.
Gene: Protein-coding gene on chromosome 19 (44,699,151 to 44,710,718, forward strand). Ensembl gene ENSG00000213892.
Subcellular location: Secreted
Gene Ontology:
Molecular function: identical protein binding
Biological process: sensory perception of sound
Cellular component: extracellular region; stereocilium tip
Genetic constraint (gnomAD): Loss-of-function variants: 30 observed, 35.72 expected, observed/expected ratio (o/e) 0.84, 90% interval 0.63 to 1.14. The upper end of that interval is the gene's LOEUF score, 1.14, which puts it in group 4 of 6, group 1 being the genes least tolerant of losing a copy. Missense variants: 505 observed, 543.57 expected, observed/expected ratio (o/e) 0.93, 90% interval 0.86 to 1. Synonymous variants: 253 observed, 246.3 expected, observed/expected ratio (o/e) 1.03, 90% interval 0.93 to 1.14.
Gene-disease validity (ClinGen):
ClinGen rates the evidence that CEACAM16 causes each of these diseases.
nonsyndromic genetic hearing loss (autosomal recessive): Strong. A disease characterized by hearing loss that is not part of a larger syndrome.
nonsyndromic genetic hearing loss (autosomal dominant): Moderate.
Homologues: Orthologues: chimpanzee CEACAM16 (99% identical), macaque CEACAM16 (96% identical), dog CEACAM16 (90% identical), mouse Ceacam16 (89% identical), rat Ceacam16 (88% identical), pig CEACAM16 (88% identical), rabbit CEACAM16 (86% identical), guinea pig CEACAM16 (83% identical), tropical clawed frog ceacam8 (18% identical), tropical clawed frog ceacam8l (15% identical), tropical clawed frog ceacam19lm (13% identical), tropical clawed frog ceacam20 (13% identical). Paralogues in human: CEACAM1 (30% identical), CEACAM5 (29% identical), CEACAM6 (26% identical), CEACAM8 (24% identical), PSG9 (24% identical), PSG6 (23% identical), PSG7 (23% identical), PSG3 (23% identical), PSG4 (23% identical), PSG8 (23% identical), PSG1 (22% identical), CEACAM21 (22% identical), and 12 more.
Diseases named in the same sentence as CEACAM16 in open-access papers:
CEACAM16 is named in the same sentence as 13 diseases in open-access papers, as found by Europe PMC text mining. Sharing a sentence is not in itself a finding about the gene and the disease. The quoted sentences say what the papers report.
deafness (5 papers, 2014 to 2024). An inherited or acquired condition characterized by the complete loss of the ability to hear from one or both ears. "Dominant and recessive mutations in CEACAM16 have been reported to cause postlingual and progressive forms of deafness in humans." (PMID 31249509, 2019). "In addition to providing a model for studying the causes of one form of human hereditary deafness, the Ceacam16βgal mouse may also be suitable for testing whether the onset of deafness in affected patients could be prevented by virally mediated expression of CEACAM16 in the cochlea." (PMID 31249509, 2019).
hearing loss (5 papers, 2017 to 2024). "Here we reported a novel missense variant in CEACAM16 gene causes autosomal dominant non‐syndromic hearing loss." (PMID 35292975, 2022). "Segregation analysis revealed that only the heterozygous A‐to‐G transition at position 763 in exon 5 of CEACAM16 (NM_001039213: c.763A>G; (p.Arg255Gly) cosegregated with the hearing loss phenotype." (PMID 35292975, 2022). "In another family with hearing loss, the p.Gly169Arg variant at Ig‐C like domain A was assumed to change the spatial structure of CEACAM16 and decrease stability and the polymerizing ability of the protein." (PMID 35292975, 2022). "In summary, we implicate a novel variant in CEACAM16 as the genetic cause of progressive hearing loss in a large Chinese pedigree." (PMID 35292975, 2022). "Both Ceacam16 and Col11A2 encode proteins that are components of the tectorial membrane (TM), and their deletion disrupts TM structure, resulting in hearing loss." (PMID 29073148, 2017). "To date, the specific function of the protein encoded by CEACAM16, as well as the pathogenetic mechanisms underlying hearing impairment of patients harboring variants in this gene, remain unclear." (PMID 35292975, 2022). "The loss of Ceacam16 therefore accelerates age-related degeneration of the tectorial membrane leading, as in humans with mutations in CEACAM16, to a late-onset progressive form of hearing loss." (PMID 31249509, 2019). "The remaining gene variants in CEACAM16, COL11A1, COL9A2, DIAPH1, TCOF1 were tested for segregation with the hearing loss phenotype in the extended family." (PMID 35292975, 2022). "We suggest that this variant leads to increased secretion of mutant CEACAM16 protein in vitro, uncovering a putative novel mechanism underlying DFNA4B‐related hearing loss." (PMID 35292975, 2022). "The amount of TM-matrix that can be lost before there is an impact on low-frequency responses is therefore high and may explain why a hearing impairment is not detected in humans with recessive mutations in CEACAM16 until the second decade of life." (PMID 31249509, 2019).
autosomal dominant nonsyndromic deafness (2 papers, 2012 to 2022). "Carcinoembryonic antigen-related cell adhesion molecule 16 (CEACAM16), an adhesion protein concentrating at the top of OHC stereocillia, interacts with TECTA and mutation of CEACAM16 results in autosomal dominant nonsyndromic deafness (ADNSHL) at the DFNA4 locus." (PMID 22942697, 2012).
liver disease (1 paper, 2025). "As for carcinoembryonic antigen‐related cell adhesion molecule 16 (CEACAM16), despite reported associations with liver disease and function in the literature, this protein does not appear to have been previously reported to be associated with alcohol consumption." (PMID 40556615, 2025).
sensorineural hearing loss (1 paper, 2025). "We also examine the contributions of genes such as TECTA, TECTB, and CEACAM16, whose mutations disrupt TM integrity and lead to sensorineural hearing loss." (PMID 40901670, 2025).
CEACAM16 also shares sentences with these, for which no sentence is quoted: Hearing impairment (2 papers); Alzheimer disease (1); asthma (1); diseases of the circulatory system (1); gout (1); infection (1); nonsyndromic hearing loss (1); type 2 diabetes (1).